IL10 (interleukin 10)
Diseases named in the same sentence as IL10 in open-access papers (continued):
Sharing a sentence is not in itself a finding about the gene and the disease.
cancer (continued). "In accordance with previous findings, IL‐10 in ascitic fluid was augmented at the increase in the cancer stage and this correlates with GLUL levels in TAMs." (PMID 34260142, 2021). "Gene Ontology (GO) analyses indicated certain pathways were involved, including the activation of MAPK activity, which was reported to induce IL-10 production in regulatory T cells, which mediate immune paralysis in cancer." (PMID 34925696, 2021). "It was shown that monocytes from healthy subjects are able to acquire the phenotype and suppressive function of M-MDSCs under exposure to cancer cells and the specific microenvironment with a high level of interleukin 10 (IL-10) or prostaglandin E2 (PGE2)." (PMID 33803806, 2021). "The HMC3 cells were stimulated with a cytokine cocktail known to originate from cancer cells, that was comprised of interleukins IL-4, IL-13, IL-10, growth factors TGFβ1/TGFβ2, and chemokine CCL2." (PMID 34566949, 2021). "Other factors are also associated, such as DCs, interleukin 10 (IL-10), TGF-β, Treg cells, and reduced CD8+ T cell priming and infiltration, which together cause immune evasion, and reduced cancer immunosurveillance." (PMID 34968365, 2021). "Other molecules, including PRDM1 (BLIMP1), NFAT, and IL10, are involved in T-cell activation and contribute to T-cell exhaustion in cancer." (PMID 34305618, 2021). "The preventive effect, antigen-induced Th1- and Th2-type cytokine responses in inducible BALT, Treg population, and IL-10 induction should be assessed using real antigens from infections or cancers in future studies." (PMID 34291725, 2021). "Cancer-associated inflammation is mediated by infiltration of leukocytes and secretion of various cytokines such as TNF-α, IL-6, IL-8, TGF-β1, and IL-10." (PMID 34778599, 2021). "The inflammatory response from cancer cells promotes the infiltration of neutrophils, which benefits cancer progression via the secretion of IL-2, IL-6, IL-10, TNFα, and VEGF." (PMID 34503128, 2021). "IL-10 has been recognized as one of the most potent and multifunctional immunoregulatory cytokines that has a profound effect on anti-cancer T cell responses." (PMID 34769278, 2021). "Collectively, these findings indicate that high doses of IL-10 can induce pro-inflammatory responses in healthy participants as well as patients with autoimmune disease and cancer." (PMID 34234779, 2021). "MDA-7/IL-24, a multifunctional cytokine and member of the IL-10 gene family, displayed profound anti-cancer activities in pre-clinical studies and in Phase I clinical trials in patients with advanced cancers." (PMID 35008495, 2021). "The loss of PTEN leads to aggressive expression of IL-6, IL-10 and VEGF, thereby facilitating the immune response against cancer cells." (PMID 34381028, 2021). "TGF-β and IL-10 are potent immunosuppressive cytokines which induce Tregs that in turn allow cancer cells to escape immune surveillance." (PMID 34068008, 2021). "We used RT-qPCR to screen mRNA levels of a variety of inflammatory factors closely related to the development of cancer, including IL-6, IL-10, IL-17A, and Hsp90α, in LINC00673 and control stable cells." (PMID 34094965, 2021). "Nevertheless, other studies in cancer have shown that PD-L1 can mediate IL-10-independent suppression by B cells." (PMID 33995344, 2021). "Immunosuppressive cytokine markers TGFB1 and IL10 were significantly enriched in the EMT-high group of almost all cancer types compared to those in the EMT-low." (PMID 35096592, 2021). "Cytokine levels from clinical studies indicate, that in CRC patients serum IL-10 levels increase over time during cancer progression." (PMID 35008550, 2021). "M2 macrophages, which exert an immunosuppressive phenotype by the secretion of anti-inflammatory cytokines (i.e., IL-4, IL-10, and IL-13), were the only pro-cancer immune cells that were higher in high-thermogenesis TNBC." (PMID 34071012, 2021).
cancer (continued). "The infiltrating MDSC induces EMT of cancer cells by upregulating TGF-β1, VEGF and IL-10, thus promoting cancer metastasis to the lungs after surgery." (PMID 34689842, 2021). "For example, the promoter of IL10 has been shown to be either hypermethylated or hypomethylated depending on the type of cancer." (PMID 34901003, 2021). "In a lung cancer mouse model, it has been demonstrated that IL-10 and TGFβ secreted by KRAS mutated cancer cells, induce the conversion of CD4+ CD25- T-cells into FOXP3+/CTLA4+/CD122+ T regulatory cells (Tregs)." (PMID 33777798, 2021). "Inflammatory cytokines such as TNF-α, IL-6, TGF-β, and IL-10, have been shown to participate in cancer initiation and progression, depending on the balance of pro- and anti-inflammatory cytokines and their relative abundance." (PMID 33466674, 2021). "We detected higher levels of TNFα, IL-1Rα, MCP-1, IL-8, IL-10 and IL-17 in the plasma of cancer patients." (PMID 34950660, 2021). "In various cancers, serum engagement of IL-10 was very much evident, concurrently in immune-stimulation and immunosuppression." (PMID 34336101, 2021). "Due to uncertain therapeutic safety and effectiveness, IL-10 signaling blockades remaina region for explorationand are being used in cancer immunotherapy." (PMID 33401586, 2021). "In this study, cancer patients with higher concentration of TNF-α, IL-2R, IL-6, IL-8, and IL-10 had higher risk of death." (PMID 33735106, 2021). "Since the 1990s, after the discovery of IL-10, its role in cancer immunotherapy has raised eyebrows thanks to its complexity." (PMID 34336101, 2021). "The anti-inflammatory cytokines such as IL-4 and IL-10, which were considered protected cytokines in the past, become a double-edged sword in the protection of cancer." (PMID 34803728, 2021). "The inflammatory cytokines IFN-γ, IL-6 and IL-10 were also found at significantly higher levels in the cancer secretome compared to the normal secretome." (PMID 33540635, 2021). "On the contrary, M2 macrophages can provide a nutritional advantage to cancer cells when stimulated by IL-4, IL-6, IL-10, IL-13, transforming growth factor β (TGF-β), vascular endothelial growth factor (VEGF) and other M2-specific cytokines." (PMID 34717710, 2021). "Tregs produce and release suppressor cytokines, including TGF-β and IL-10, that regulate cancer immunity." (PMID 34248973, 2021). "Tregs favor cancer immune evasion by producing the immune-suppressive cytokines IL-10 and IL-35 and transforming growth factor-β (TGF-β), which hamper APC functions or induce apoptosis of APCs." (PMID 34571894, 2021). "The released IL10 suppresses the maturation of DCs by reducing the expression of T-cell stimulatory molecules, and also intensifies cancer stemness through the JAK1/STAT1/NFkB pathway." (PMID 33535613, 2021). "Secreted by various immune cells, IL10 participates in the suppression of cancer-mediated inflammation." (PMID 34359731, 2021). "Analysis of cytokines showed significant enrichment of immunosuppressive cytokines—TGFB1 and IL10—in the EMT-high group of almost all cancer types." (PMID 35096592, 2021). "The decrease in IL-12 correlates with cancer progression and metastasis and is probably dependent on the upregulation of IL-10 induced by AnxA1." (PMID 34571894, 2021). "Th2 cytokines,such as IL-4 and IL-10, are increased in late-stage cancers in comparison to Th1 cytokines that are more prevalent in the early-stage." (PMID 34025655, 2021). "Several inflammatory mediators, such as TNF-α, IL-6, TGF-β, and IL-10, have been shown to play a role in cancer progression." (PMID 34485118, 2021). "Secretion of IL-4 and IL-10 by cancer cells has been shown to confer drug-induced resistance, by specifically inhibiting apoptotic pathways." (PMID 34307156, 2021). "Secreted from activated skeletal muscle, IL10 is mostly described as an anti-inflammatory regulator with an indirect impact on cancer." (PMID 34359731, 2021).
cancer (continued). "Several studies have reported that cytokines such as IL-6, IL-8, IL-10, TGF-β, and TNF-α are detected in cancer-associated exosomes, leading to cancer progression and drug resistance." (PMID 34771423, 2021). "Both TGF-β and IL-10 function at the crossroads of immune stimulation and immune suppression in cancer and their role in immune pathology is unclear." (PMID 34068008, 2021). "M2-type TAMs, on the contrary, secrete anti-inflammatory agents such as transforming growth factor-β (TGF-β), interleukin-10 (IL-10), and epidermal growth factor, which inhibit immune responses and induce angiogenesis and carcinoma metastasis." (PMID 33573359, 2021). "Next, we used cBioPortal to evaluate the correlations between the levels of FGL2 and the cancer-promoting cytokines measured above (IL-10, MMP9, CCL5, TIM-3, IL-13, VCAM1, M-CSF and FGF-7) in ESCA tissues." (PMID 33323552, 2020). "IL10 signaling pathway is a complex molecular network comprising a minimum of 37 molecules and 76 reactions to support cancer development." (PMID 32219066, 2020). "Interleukin-10 (IL-10) is one of the cytokines released by M2 macrophages and has been subsequently found to play multiple roles in cancer development." (PMID 33372604, 2020). "This pattern appears correspondent with the known biological conditions typically induced by metastatic cancer cells as the immunosuppressive function (IL-10), vasculogenic action (VEGF), and hypoxic condition (IL-1b)." (PMID 32630302, 2020). "IL10 is best studied as an anti-inflammatory, immune suppressive cytokine that contributes to promoting cancer aggressiveness by acting on immune cells to suppress the antitumour immune response." (PMID 32802517, 2020). "They found that swimming increases INF-γ and TNF-α cytokines; however, it decreases anti-inflammatory cytokines such as TGF-β and IL-10 in mice models with cancer." (PMID 32405368, 2020). "TAMs greatly contribute to the aggressive progression of cancer by releasing cell-stimulating growth factors and cytokines, including IL-6, IL-10, and TNF-α." (PMID 32222879, 2020). "This is at least because the production of IL-10 during inflammatory conditions, such as cancer and infectious diseases, has been shown to inhibit the inflammatory immune responses mediated by different immune cells." (PMID 32931721, 2020). "IL10 is an anti-inflammatory, immune-suppressing cytokine, and IL10 serum levels in cancer patients are positively correlated with Gleason scores." (PMID 33005103, 2020). "Our results showed that IDO and IL-10 mRNA levels were increased about 27.99 fold and 8.54 fold in cancer patients’ cells over control cells, respectively, but ARG1 levels were increased by 1.68 fold." (PMID 33679700, 2020). "Alternatively, stimuli such as IL-4, IL-14, IL-10 can induce macrophages towards an anti-inflammatory and cancer-promoting M2 phenotype." (PMID 33329573, 2020). "The main factors affecting the biological activity of cancer cells are IL-10, IL-6, TGF-β, VEGF, CCL18, CCL22, and microRNA." (PMID 32456078, 2020). "IL-6 and IL-10 create a favorable environment to support tumorigenesis by increasing the cancer cell proliferation, angiogenesis, metastasis and contribute to enhancing the immune suppression." (PMID 32508531, 2020). "IL-10, the cytokine fostering immunologic tolerance of cancer was high in NSCLC, but lower (in the control range) in NSCLC+COPD." (PMID 31090020, 2020). "In both AIT and cancer, a modified Th2 microenvironment based on IL-10 production by Tr1 and Br1 cells can lead to high levels of IgG4 expression by B cells and the establishment of immune tolerance." (PMID 32708690, 2020). "Thanks to its immunosuppressive effect on dendritic cells and macrophages, IL-10 can attenuate antigen presentation, cell maturation and differentiation, allowing cancer cells to circumvent the mechanisms of immunosurveillance." (PMID 32283655, 2020).
cancer (continued). "Although cancer-ASCs hadmore significant effects on developing IL-10- and TGF-β-producing Tregs, normal-ASCs induced IL-17-producingTregs." (PMID 31721539, 2020). "Glucocorticoids, like dexamethasone, increase the Treg cell expression with a consequent increase of IL-10, an anti-inflammatory cytokine involved in the protection of the cancer cell microenvironment." (PMID 32149076, 2020). "This analysis indicated that the biological category “Pathways in cancer” is the most enriched for IL-10 targeted genes and “Cytokine-Cytokine receptor interaction” for the IL-6 targeted genes." (PMID 32211606, 2020). "Supernatants obtained from biopsy material also exhibited a significantly higher level of IL-10 in cancer patients than in normal controls." (PMID 32488850, 2020). "Of note, IGF-1 increases the proliferation of many cancer cells, IL-10, and TGF-β1 inhibits the immune responsiveness of T cells, and VEGFA enhances angiogenesis." (PMID 32908942, 2020). "Cancerous cells secrete inflammatory cytokines like IL-10,IFN-γ which increase expression of immunosuppressive molecules, such as HLA-G." (PMID 32123232, 2020). "In the transwell invasion assay, the invasive ability of cancer cells co-cultured with Wnt5a-induced M2 macrophages was also enhanced, and this enhancement was suppressed by IL-10 neutralizing antibody." (PMID 32228612, 2020). "Considering the efficacy of the combination therapy, in all groups that received the cancer vaccine, the amount of IL-10 production was decreased by regulatory T cells." (PMID 32952954, 2020). "In the cancer pathogenesis, IL-10 was also proven to be involved in anti-inflammatory and immunosuppression functions." (PMID 32899735, 2020). "Since it is known that M2‐like macrophages support cancer cell migration, we evaluated the extent of cancer motility trough 8 μm‐pores in presence of macrophages treated for 24 h with IL10 versus glufosinate/or MSO/IL10 and then washed out." (PMID 32885605, 2020). "Upregulation of TNFα, MCP-1 and IL-10 has been consistently observed in this study and in previous in vitro and in vivo models of cancer following IgE immunotherapy." (PMID 33203088, 2020). "The cytokines and their receptors utilized through TAMs during cancer progression include IL-6, IL-12, IL-10, IL-23, TNF, and TLRs." (PMID 32283687, 2020). "TGF-β is a cytokine that induces the Foxp3+ phenotype in lymphocytes, while IL10 is an immunosuppressive factor whose increased concentration has been observed in chronic inflammation as well as in cancer." (PMID 32488850, 2020). "TNF and IL-10, are multifunctional cytokines produced by the immune system, has a wide range of biological system including a pro- and anti-cancer effect." (PMID 32693841, 2020). "CM from both cancer cell lines induced mRNAs encoding the M2 markers CD163, FN1, and IL10 in ShCtrl THP-1 cells; the induction ranged from 2- to 4-fold by CM from MCF-7 cells, and from 5- to 60-fold by CM from MDA-MB-231 cells." (PMID 33086476, 2020). "Conversely, Th2 cells demonstrate pro-cancer function via the secretion of interleukin-4 (IL-4), interleukin-6 (IL-6), interleukin-10 (IL-10), and transforming growth factor-β (TGF-β)." (PMID 32370060, 2020). "In breast cancer, promotion of the IL-10 induced immunosuppressive Treg phenotype depends on the stage of cancer, and during its formation other mediators are involved in addition to activated STAT3." (PMID 32488850, 2020). "Among these, a pivotal role is played by IL-6 and TGF-β as inducers of GMT and cancer growth, IL-10 as a modulator of immune response and the chemoattractant IL-8 as a promoter of GBM motility." (PMID 33081024, 2020). "The migration of cancer cells co-cultured with Wnt5a-induced M2 macrophages was significantly enhanced, which was reversed by IL-10 neutralizing antibody." (PMID 32228612, 2020).
cancer (continued). "In the early stage of the disease, Treg cells and their effect molecule IL-10 serve an important, protective role against cancer by maintaining immune homeostasis." (PMID 32677955, 2020). "Although attenuated, these effects were still detectable in PBMC-NKEV cocultures containing TGFβ and IL-10, a condition we included to recapitulate an immune compromised microenvironment, such as in cancer." (PMID 32231660, 2020). "It is clear that IL-10 is involved in the pathogenesis of different inflammatory pathological conditions, including several types of cancers." (PMID 32931721, 2020). "IL-10 is an anti-inflammatory and immunosuppressive cytokine that influence the course of cancer by promoting immune escape through inhibition of the antitumor activity of immune cells." (PMID 32655554, 2020). "Their expansion and migration can be induced by molecules produced during chronic inflammation and cancer, such as GM-CSF, IL-6, IL-10, IFN-γ, and VEGF." (PMID 33171792, 2020). "mRNA and protein levels of PD-L1 (P < 0.001) and IL10 (P < 0.001) were higher in carcinoma tissues than in adjacent tissues." (PMID 32724815, 2020). "Comparatively, IL10 was highly expressed in carcinoma tissues from 67 patients and adjacent tissues from 35 patients." (PMID 32724815, 2020). "Expression level of PD-L1 and IL10 in adjacent tissues and normal tissues was lower than in carcinoma tissues." (PMID 32724815, 2020). "Expression levels of PD-L1 and IL10 in carcinoma and adjacent tissues were tested by immunochemistry, Western blotting, and RT-PCR." (PMID 32724815, 2020). "A similar variability of results is also found for the anti-inflammatory cytokine IL-10 for BC patients, although in other cancers, according to a meta-analysis of 21 studies, this IL has been reported to be associated with worse outcome." (PMID 30658426, 2019). "On the other hand, exosomes also induce the expression of IL-10 in macrophages and PD-L1 in cancer cells, thus resulting in the promotion of an immunosuppressive environment." (PMID 31697737, 2019). "Co-culture of macrophages and cancer cells results in an initial switch to a phenotype characterized by high expression of IL-1β and IL-10, while an MRC1 expression remains unmodified." (PMID 31697737, 2019). "In the tissue, CD4+/IL-4+ and CD20+/IL-10+ cells were positively associated with miR-21 and CD4+/IFN-β, thyroid hormone, and cancer signaling pathways were shared between miR-21, miR-31, miR-23b, miR-146a, miR-1246, and miR-150." (PMID 32082077, 2019). "The immune response related to cancer immunotherapy of GM-CSF, IL-6, and IL-10 notably involves modification of T-cell responses." (PMID 31754081, 2019). "IL-10 is a cytokine produced by CD44hi Tregs and plays a central role both in parasitic infections, intestinal inflammation, and cancer again emphasizing the involvement of similar mechanisms in different pathophysiological conditions." (PMID 31134056, 2019). "Earlier studies reported that IL-35, similar to IL-10, to be crucial for suppressing inflammatory responses during auto-immunity and cancer." (PMID 31031744, 2019). "IL-10 exhibits a context-dependent outcome in cancer, and administration of PEGylated IL-10 increases its half-life to avoid grade 3–4 immune-related adverse effects." (PMID 32117199, 2019). "IL-10 signaling blockades are still under exploration and are a long way from being used in cancer therapy due to unclear therapeutic efficacy and safety." (PMID 32010123, 2019). "Despite that, Bregs have been shown to play an important role in supporting cancer immune escape through the release of anti-inflammatory mediators, such as interleukin-10 (IL-10)." (PMID 31137912, 2019). "The protumorigenic effect of these genotoxins has been shown in mouse models prone to develop cancer or dysplasia, such as the IL10 knockout mice exposed to the procarcinogen AOM." (PMID 31414579, 2019).